CDK4 (cyclin dependent kinase 4)
Diseases named in the same sentence as CDK4 in open-access papers (continued):
Sharing a sentence is not in itself a finding about the gene and the disease.
glioma (continued). "Following this point of view, although the results of molecular docking supported the existence of affinity potential of TIZ with CDK1, CDK2, and CDK4, we only performed siRNA targeting CDK1 to verify the inhibitory effect of TIZ on the proliferation of gliomas." (PMID 35694267, 2022). "The results show that the expression of CDK4 and ANGPTL2 was significantly associated with CNV, indicating that the expression of CDK4 and ANGPTL2 in glioma may be affected by CNV." (PMID 36358948, 2022). "From the transcriptome data analysis results in the public database, it was found that CDK4, PBK, ANGPTL2, TMEM100, and MEX3A were significantly up-regulated in the glioma samples compared with the normal samples, whereas NEGR1 and SLC2A3 were down-regulated in the glioma samples at the mRNA level." (PMID 36358948, 2022). "Identifying these RB1 mutations is relevant to treatment, because tumors harboring inactivation of RB1 are unlikely to respond to CDK4/6 inhibitors, which have been developed and are being investigated as glioma therapy." (PMID 35610333, 2022). "In summary, NAP1L1 could promote proliferation and chemoresistance in glioma cells by interacting with HDGF and activating c-Jun to induce the expressions of CCND1/CDK4/CDK6." (PMID 34959221, 2021). "Sev exhibits an anti-tumor role in glioma, possibly via regulating HMMR-AS1/miR-7/CDK4 axis." (PMID 34719318, 2021). "Besides, the positive correlation between Pontin and six E2F1 targets (AURKA, CDK1, CDK4, CCNA2, CCNB2, E2F8) assessed by GEPIA in glioma further supported the positive regulation of E2F1 targets expressions by Pontin." (PMID 33542204, 2021). "The DDRGs signature composed of CDK4, HMBG2, WEE1, SMC3 and GADD45G could accurately predict the prognosis of gliomas." (PMID 34123852, 2021). "Cdk4 is required for ErbB-2-driven mammary tumorigenesis, DMBA/TPA-induced skin tumor development, Men1+/−-driven neuroendocrine tumorigenesis, PDGF-induced glioma and APCMin/+-driven adenoma." (PMID 33806417, 2021). "Glioma-related ctDNAs included 1p/19q, MDM2, ERBB2, IDH1, CDKN2A, CDK4, PDGFRA, CCNE1, MET." (PMID 32973641, 2020). "Besides, FOXO1 knockdown elevated protein levels of P‐PI3K, P‐AKT, CDK4, CCND1, c‐JUN, N‐cadherin and vimentin in glioma cells." (PMID 32902145, 2020). "Moreover, the ctDNAs in the metastatic brain tumors included ALK and MDM2, and glioma-related ctDNAs included 1p/19q and MDM2 followed by frequencies of ERBB2, IDH1, CDKN2A, CDK4, PDGFRA, CCNE1, MET." (PMID 32973641, 2020). "Here we demonstrate that glioma organoids and PDOXs accurately maintain distinct genetic backgrounds of parental tumors, including gene amplifications of EGFR, PDGFRA, MET, MDM2/4, and CDK4/6, which are difficult to derive and preserve in vitro." (PMID 33009951, 2020). "In addition, we investigated the potential biological process through which BACE2 promotes glioma malignant development and evaluated the expression levels of some key regulators of the cell cycle, including CDK2, CDK4, cyclin D1, p21 and p27." (PMID 31856384, 2020). "The patients with higher CDK4 expression had shorter survival rate than those of the counterparts in grade III primary glioma, but not in grades II and IV." (PMID 32860670, 2020). "From the analysis above, we observed that several cell cycle related genes, such as CDKN2A/2B (14% vs. 3%), CDK4 (10% vs. 0) and RB1(10% vs. 0), were dominant in recurrent gliomas as compared to primary gliomas, so we further clustered the mutated genes according to their functional characteristics." (PMID 31690770, 2019). "The protein CDK4 is not detected in any normal brain cell, while it is present at some level in most glioma samples." (PMID 31500569, 2019). "Since CyclinD1 and CDK4 facilitate cell proliferation in various cells, we then investigated whether they involved in PLD1-resultant proliferation of glioma cells." (PMID 28915652, 2017).
glioma (continued). "Similar results were seen in LS0082 and SNB19 glioma cells—knocking down ATRX prevented CDK4 inhibitor induced senescence and MDM2 levels did not decrease." (PMID 25803170, 2015). "No other loci, such as MDM2 and CDK4, genes recurrently amplified in gliomas, were amplified in ODA14." (PMID 25378339, 2014). "It is worth noting that there may be other biomarkers for response such as amplification of D-type cyclins, CDK4 or CDK6 amplifications- all of which are present in DIPGs and other pediatric high-grade gliomas." (PMID 24098593, 2013). "Besides EGFR, which is found overexpressed in 40% of gliomas, the genes N-MYC, C-MYC, PDGFR-α, MYB, K-RAS, CDK-4 and MDM2 are the most commonly amplified oncogenes in gliomas." (PMID 18713462, 2008). "In T98G glioma cells, serum stimulates the phosphorylation of cyclin D3-bound CDK4 but not cyclin D3-bound CDK6." (PMID 17092340, 2006). "As analysed in the same cyclin D3 co-immunoprecipitations in T98G glioma cells, serum stimulates the activating phosphorylation of CDK4 but not that of the related CDK6." (PMID 17092340, 2006). "Selective inhibition of CDK4/6 was reported to suppress the tumor growth and may enhance the sensitivity of glioma cells to TMZ, suggesting that CDK4/6 inhibition may be a favorable treatment strategy for glioma and overcome TMZ resistance." (PMID 35991838, 2022). "Furthermore, CD1 and CDK4 are critical for both the glioma cell and the TME as the lack of CDK4 prevents glioma cell development, and the absence of CD1 alone had an opposite effect." (PMID 34687436, 2022). "The results show that the expression of CDK4 and ANGPTL2 in glioma may be affected by CNV." (PMID 36358948, 2022). "Besides, Western blotting revealed that miR‐5188 inhibition led to reduced protein levels of P‐PI3K, P‐AKT, CCND1, CDK4 and c‐JUN, but increased protein levels of FOXO1 in glioma cells with SP1 overexpression, suggesting that miR‐5188 was enhanced by SP1 through the PI3K/AKT pathway." (PMID 32902145, 2020). "Interestingly, miR-124 inhibited the migration and invasion of glioma cells through down-regulation of ROCK1, SOS1, CDK4, STAT3, and PPP1R13L expression, indicating miR-124 may be a valuable biomarker for glioma." (PMID 28060761, 2017). "In addition, a 24 h exposure to CAPE (50 μg/ml) inhibited the growth of C6 glioma cells, inducing cell cycle arrest at the G1 subphase after a 24 h incubation, decreasing the CDK2/cyclin E and CDK4/cyclin D activity and inhibiting Rb phosphorylation by increasing p21, p27 and p16 expression." (PMID 26694491, 2015). "The upregulated gene, CDK4, acts downstream of Raf and regulates cell proliferation; thus, increased CDK4 expression may negate the inhibition of cell proliferation resulting from downregulation of ARAF, leading instead to the survival of glioma cells." (PMID 25007077, 2014). "CDK4 and PDGFRA amplification were rare in GII/IIIs overall, suggesting that these events may play a role in the progression of a lower grade to a higher grade glioma." (PMID 24614622, 2014). "However, there is no report in support of the role of CDK4 in glioma cell invasion." (PMID 34719318, 2021). "In this study, 24/213 (11%) glioma patients with presumed tumor predisposition carried GVs in CPGs that potentially sensitize them to targeted therapies not routinely used in glioma patients, such as PARP, immune checkpoint, EGFR, or CDK4/6 inhibitors." (PMID 41546701, 2026).
glioblastoma (155 papers, 2010 to 2026). The most malignant astrocytic tumor (WHO grade IV). "CDK4, which is involved in the retinoblastoma signaling pathway, is associated with dismal survival in oligodendroglioma, astrocytoma, and glioblastoma." (PMID 36998447, 2023). "Our finding that the CDK4/MDM2 co-amplicon was associated with CCND2 gain was also seen in glioblastoma multiforme." (PMID 28643781, 2017). "Some of these alterations, such as del (1p36), del (2p21), +7, del (6q27q29)/−6, EGFR (7p11.2), MDM2 (12q15) and CDK4 (12q14.3) amplification, −10, amplification of 15q24.1, del (17p13)/−17, −19, −22 were known to be associated with glioblastomas." (PMID 23472076, 2013). "In another study of glioblastoma, chromosome 12q13.3-14.1 amplification caused over-expression of genes (CDK4 and CENTG1) and a microRNA (hsa-miR-26a), all of which were demonstrated to contribute to the progression of the cancer." (PMID 20537188, 2010). "Dysregulation of the CDK4/6‐p16‐RB1 pathway is a hallmark of glioblastoma." (PMID 38899374, 2024). "In addition, the miR-17-92 family (including miR-20a and -19a) rendered proneural (PN) glioblastoma (GBM) more susceptible to CDK4/6 inhibition than other subtypes." (PMID 34439268, 2021). "In glioblastoma xenograft models, it has been demonstrated that a combination of CDK4/6is with oncolytic viruses promoted calreticulin exposure and extracellular ATP secretion, which indicated the enlargement of immunologic cell death in glioma cells." (PMID 39593745, 2024). "Under the combined treatment of Resveratrol (RSV) and RO4929097, CDK4 inhibits the population of glioblastoma stem cells with a more invasive phenotype, also triggers apoptosis by pathways blocking the autophagic flux." (PMID 38672496, 2024). "Of the 34 overexpressed tyrosine kinase genes, MDM2 and CDK4 in glioblastoma, 22 copy number amplifications (64.7%) were observed." (PMID 38363490, 2024). "50% of glioblastoma patients have been found to harbour alterations in cyclin D1/CDK4/6-CDKN2A(p16INK4A)-Rb axis; hence, the use of CDK inhibitors in the treatment of glioblastoma warrants further investigation." (PMID 38212807, 2024). "CDK4/6 inhibitors have an immense potential for treatment of CDK4/6 positive CNS tumors such as glioblastoma and metastatic breast cancer." (PMID 38999983, 2024). "CDK4 was focused as a target during in silico study because it is reported to be significantly more elevated in glioblastoma than CDK2 and CDK6." (PMID 39650055, 2024). "Despite the centrality of cellular proliferation in glioblastoma tumourigenesis, the clinical activity of CDK4/6 inhibitors has been limited." (PMID 38212807, 2024). "In a different cancer model such as glioblastoma cells (GBM), the dramatic reduction of an important regulator of lysosomal function such as cyclin-dependent kinase 4 (CDK4) induced an impaired autophagic function, causing the collapse of the system and a following apoptosis." (PMID 38994937, 2024). "It is reported that co-deletion of CDKN2A and CDKN2C confer Palbociclib-sensitivity in glioblastoma and soft tissue sarcoma, demonstrating that amplification of CDK4 benefits from the CDK4/6 inhibitor." (PMID 38369555, 2024). "With our previous study, we also demonstrated the activation of the mTOR pathway in glioblastoma as a resistance mechanism to CDK4/6 inhibition." (PMID 38927958, 2024). "Combining Notch inhibitors with resveratrol to target CDK4 can modulate the invasiveness of glioblastoma." (PMID 38672496, 2024).
glioblastoma (continued). "While MDM4 alterations were absent in FGFR3-TACC3 fusion-positive gliomas, there is an association with a higher prevalence of MDM2 alterations and CDK4 amplifications, which can be found in 19% and 10%, respectively, of fusion-positive glioblastoma." (PMID 35955806, 2022). "Similar patterns of high MDM2/CDK4 amplification with large derivative chromosomes were observed in human glioblastoma, and were assigned to chromothripsis, with aggregation of double minute chromosomes." (PMID 35053440, 2022). "Clinical studies have also demonstrated that CDK4/6 inhibitor alone showed sub-optimal efficacy for recurrent glioblastoma." (PMID 34572040, 2021). "The cases with CDK4 amplification clustered in the Other subgroup that contained six of the ten total IDH-wild-type glioblastoma cases with CDK4 amplification." (PMID 34572759, 2021). "Mutations in the cell cycle G1 phase genes CDKN2A/2B, CDK4, and RB1 were mutually exclusive in this series, except for two heterozygous germline RB1 point mutations, and were present in 79.3% of glioblastoma IDH-wild-type cases." (PMID 34572759, 2021). "In most glioblastoma multiforme a dysregulation of the pRb signaling pathway is observed, as well as CDK4/6 amplification leading to a dysfunctional cell cycle transition from G1 to S phase." (PMID 34202589, 2021). "The most common is CDK4 gene rearrangement or copy number abnormalities (4/7, 57.1%); all were found in glioblastoma." (PMID 34712610, 2021). "With respect to cell cycle control, loss-of-function mutations of cyclin dependent kinase inhibitor 2A/B (CDKN2A/B) can be found in half of all glioblastoma specimens, and cyclin-dependent kinase 4 (CDK4) is often highly amplified." (PMID 34067762, 2021). "The CDK4 alterations occur in 23 cancer types, mostly in sarcoma (17.65%), glioblastoma (13.85), and adrenocortical carcinoma (6.59%)." (PMID 33668805, 2021). "Our data suggest that abemaciclib will be more effective in glioblastoma with the coexistence of CDK4/6 and c-Met alterations due to its dual functions." (PMID 33498427, 2021). "Activation of the CDK4-Rb pathway is often observed in human cancers; for example, CDK4 amplification is observed in ~50% of glioblastomas." (PMID 34771669, 2021). "In glioblastomas, the Rb protein is usually inhibited either by a Rb gene deletion or by CDK4 and CDK6 gene amplification, thus promoting tumor cell proliferation." (PMID 32650495, 2020). "Previous preclinical studies have shown that a combination of CDK4/6 inhibitors, palbociclib, or abemaciclib with everolimus or altiratinib resulted in longer OS than treatment with CDK4/6 inhibitors alone in glioblastoma mouse models." (PMID 33271970, 2020). "CDK4/6 amplification has been observed in adult glioblastoma, and some studies have demonstrated that CDK4/6 inhibitors prevent cell proliferation and tumor growth in NOD-SCID mouse models." (PMID 33271970, 2020). "In the present study, we demonstrated that the flavonoid tectorigenin promoted p21 expression, decreased the levels of CDK4 and phosphorylated RB protein, triggered G0/G1 cell cycle arrest, and eventually attenuated the proliferation of glioblastoma cells." (PMID 33321738, 2020). "Moonlight identified the cell cycle kinase CDK4 as an oncogene in glioblastoma multiforme, with the highest normalized peak score (1164)." (PMID 31900418, 2020). "Even for the new generation of specific CDK4/6 inhibitors, the combination with first- and second-line cytotoxic therapy in glioblastomas showed antagonist and synergic effects depending on the combination." (PMID 31480389, 2019).
glioblastoma (continued). "For example, downregulation of STIM1 expression inhibited glioblastoma U251 cell proliferation by inducing cell cycle arrest in the G0/G1 phase through regulation of p21Waf /Cip, cyclin D1 and CDK4." (PMID 31564210, 2019). "Further molecular testing illustrated features more consistent with glioblastoma: multiple large chromosomal aberrations including loss of whole chromosome 1 and 2q; gain/amplification of MYCN, MET, and CDK4; loss of CDKN2A/B; and an ATRX mutation." (PMID 30738431, 2019). "CDK4 (cyclin dependent kinase 4), yet another candidate gene for glioblastoma, is responsible for the cell cycle’s G1 to S transition but is also involved in a variety of cancers." (PMID 30871102, 2019). "These represented additional oncogene containing regions that are amplified in glioblastoma, with CDK4 being in one and MDM2 (murine double minute homolog 2) in the other." (PMID 28655341, 2017). "High-level focal amplifications of EGFR, PDGFRA, and CDK4 were detected in affected glioblastoma samples." (PMID 28638988, 2017). "There was a significant increase in expression of p21, and this was tightly linked to the reduction in CDK4 and CCND1 in all glioblastoma cells after CKD5 treatment." (PMID 27852054, 2017). "LY2835219, an ATP-competitive dual inhibitor of CDK4/6, is an orally bioavailable drug in glioblastoma, acute myeloid leukemia, mantle cell lymphoma, colon and lung xenografts." (PMID 26909611, 2016). "For example, the RB1 pathway is inactivated in all glioblastoma tumors but is caused either by somatic RB1 mutations, CDKN2A/B mutations, or CDK4 amplification." (PMID 27126562, 2016). "Common alterations in the cyclin D1-cyclin-dependent kinase 4/6-retinoblastoma 1 pathway in glioblastoma make PD0332991 also an interesting drug for the treatment of glioblastoma." (PMID 26649278, 2015). "Deletion of CDKN2A and simultaneous overexpression of CDK4 in mice astrocytes generates high proliferating immortal cells and is also studied as a model for glioblastoma development." (PMID 25954815, 2015). "In another study, among the 5 glioblastomas that contained amplification of either CDK4 or MDM2, only one tumor had both amplified." (PMID 22691727, 2012). "In a survey of 456 glioblastomas, 13.4% had amplifications of CDK4 but only 9.2% had amplification of MDM2." (PMID 22691727, 2012). "Approximately 78% of glioblastoma show alterations in the p16INK4a/CDK-4/Rb signalling pathway." (PMID 38674436, 2024). "We have previously reported a partial response that lasted for 10 years in a patient with glioblastoma with CDK4 amplification and FGFR3-TACC3 chromosomal fusion, treated with bevacizumab and valproic acid, that targeted multiple pathways associated with tumor progression and angiogenesis." (PMID 38837109, 2024). "In addition, CDK4/6is have also been used as an adjuvant therapy to radiation therapy for the treatment of glioblastoma, and they were observed to provide a survival advantage in mice models." (PMID 39593745, 2024). "Whilst we reported potent inhibition of glioblastoma cell proliferation with 1, given the unique cytotoxic profile following 1 treatment, we sought to validate whether 1 was still inhibiting CDK4/6." (PMID 38212807, 2024). "This could be important, since the activation of the c-MET/TrkA-B pathways was described as being involved in therapeutic resistance of glioblastoma to CDK4/6i, and c-MET inhibition with altiratinib in combination with CDK4/6i can be effective in this setting." (PMID 37835528, 2023). "Some studies have shown that the CDK4/6 inhibitor can overcome temozolomide resistance and reduce the number of inhibitory M2-macrophages in glioblastoma, although the phase II clinical trial for recurrent glioblastoma patients has failed." (PMID 36998447, 2023). "None of the de novo RRD glioblastomas (0/9, 0%) had CDK4 amplification, and two tumors had truncating mutations in RB1 (2/9, 22%)." (PMID 38079020, 2023).